CGAS (cyclic GMP-AMP synthase)
Diseases named in the same sentence as CGAS in open-access papers (continued):
Sharing a sentence is not in itself a finding about the gene and the disease.
tumor (continued). "Intriguingly, several tumor cell types exploit autophagy and MOM permeabilization-driven activation of caspase 3 to avoid anti-tumor immune responses elicited by radiotherapy through mtDNA-dependent cGAS signaling." (PMID 37175888, 2023). "Importantly, the DNA released by dying HCC cells stimulates the cGAS-STING signaling pathway in CD103+ DC and promotes type I IFNs production, thereby enhancing the anti-tumor function of CD8+ T and NK cells." (PMID 37920470, 2023). "Moreover, it is unclear how chromosomally unstable tumours adapt to CIN and evade immune surveillance that would arise from cGAS–STING activation and a downstream type I interferon (IFN) response." (PMID 37612508, 2023). "This caution is needed because both prolonged activation and inadequate activation of the cGAS-STING pathway can result in unwanted chronic inflammation, which may promote tumor survival and metastasis." (PMID 38139802, 2023). "It is tempting to speculate that MLKL-dependent pore formation may facilitate release of mtDNA to stimulate cGAS/STING, which in turn induces the first wave of IFN within the necroptotic tumor cells." (PMID 38196632, 2023). "In tumor microenvironment, HMnPMH can be degraded to release Mn2+ and STING agonists, which can promote the release of type I interferon and proinflammatory factors by continuous activation of cGAS-STING pathway." (PMID 37153576, 2023). "Activation of cGAS by cytosolic DNA induces STING to phosphorylate and activate TBK1 and drive Type I interferon (IFN) pathway activation, which has the potential to induce an effective anti-tumor immune response." (PMID 37568764, 2023). "Preclinical models suggest that DNA methyltransferase inhibitors and STING agonists may rescue the cGAS-STING pathway, allowing remodeling of the tumor microenvironment, improved anti-tumor immune responses, and more durable clinical outcomes." (PMID 37173897, 2023). "Even if there is only a low level of dsDNA (less than 104mg/ml) or even no dsDNA in the cytoplasm, Mn2+ can activate the cGAS-STING signaling pathway to play the similar anti-tumor, antiviral and anti-bacterial roles." (PMID 36926351, 2023). "DDR inhibitors or DNA-interacting agents can increase the surface expression of PD-L1 and/or activate the cGAS-STING pathway, mediated by cytosolic DNA sensors, leading to Type I interferon stimulated gene (ISG) expression and tumour-infiltrating cytotoxic T-lymphocytes." (PMID 36918931, 2023). "Based on these results, we concluded that the synthetic lethality by which POLQ and BRCA2 suppress tumor cells is a distinct mechanism independent of cGAS and STING." (PMID 36976649, 2023). "Notably, inhibition of lncRNA RP11‐770J1.4 prompted activation of cGAS–STING‐related ISGs, highlighting its role as an immune‐related lncRNA that modulates the tumor microenvironment." (PMID 38116063, 2023). "As the second message, cGAMP, might activate innate and adaptive immunity in mice via the cGAS-STING-IRF3 pathway, thereby triggering the generation of cytokines and immune cells to destroy tumour cells." (PMID 37162544, 2023). "One possible cause for this discrepancy between the two tumor models is the fact that MC-38 tumor cells express cGAS but RM-9 tumor cells do not express it." (PMID 38067390, 2023). "In line with this, our in‐depth analysis revealed that RA‐induced NF‐κB and type I IFN activation in tumor cells depended on the cGAS/STING as silence of cGAS or STING, but not RIG‐1, MDA‐5, or TLR3, abolished NF‐κB and type I IFN activation." (PMID 36876644, 2023). "Leveraging our understanding of the mechanisms of cancer-mediated cGAS–STING pathway control and how cGAS–STING signalling can be beneficial to the tumour could identify novel therapeutic targets in chromosomally unstable cancer." (PMID 36876871, 2023). "Thus, we assessed how POLQ inhibition, with its observed effects on cGAS-STING signaling, influences the tumor immune response." (PMID 36976649, 2023).
tumor (continued). "Based on our current findings and previous reports, the expression of cGAS and STING in tumor cells might be regulated through different epigenetic alterations, such as histone methylation and acetylation, in pMMR/MSS CRC." (PMID 37345163, 2023). "The cGAS-STING pathway can exert anti-tumor effects independent of IFNs and autophagy, which mainly depends on the recruitment ability of STING to TBK1." (PMID 37965570, 2023). "Furthermore the induction of cGAS–STING signalling in cancer treatments such as radiotherapy, is also thought to enable the generation of spontaneous adaptive anti-tumour immunity." (PMID 37534795, 2023). "Moreover, adoptive transfer of CD8+ T cells together with GPC3144‐152 peptide also significantly reduced the tumor volumes of the TYST group, compared with those in the TYST‐sh‐cGAS group (p = 0.0189)." (PMID 37986544, 2023). "In addition to activating cGAS-STING signalling, CIN also triggers type I interferon (IFN) signalling, a cornerstone of the antiviral defence and tumour immune surveillance." (PMID 38067140, 2023). "This review presents the cGAS-STING signaling pathway, examines its primary regulatory role and function in anti-tumor responses, and explores tumor immunotherapy strategies that could pave the way for future research." (PMID 37920470, 2023). "Since the cGAS and cGAMP are maintained in the KL tumors with the restriction of STING expression, the accumulation of cGAMP can promote tumor metastasis by transferring to neighbor cells, which further contributes to KL tumor pheotypes." (PMID 37122745, 2023). "MnO2 inside the nanosystem can deplete the overexpressed GSH in tumor cells to produce Mn2+, which can activate the cGAS-STING pathway in 4T1 cells and up regulate the expression of IFN to promote dendritic cell maturation and tumor specific antigen presentation." (PMID 37153576, 2023). "However, in tumor cells, PRMT1 negatively regulates cGAS activation by methylating cGAS at R133 in its N-terminus to prevent dimerization and suppress cGAS/STING signaling." (PMID 37928266, 2023). "Nanoparticles loaded with STING agonists activate the cGAS-STING signalling pathway within the TME, resulting in IFN-β production and the activation of antigen-presenting cells, thereby stimulating the activation of tumour-reactive cytotoxic T cells." (PMID 37448962, 2023). "However, the authors also showed that higher single tumor doses of more than 12–18 Gy induced expression of the DNA exonuclease TREX1, which abolished cGAS/STING/IFN-1-mediated immunogenicity by degrading cytosolic DNA." (PMID 37834346, 2023). "Therefore, activation of cGAS-STING signal can promote the infiltration of CD8+ and CD4+ T cells at the tumor site and the cross-presentation of DCs, thus improving the effect of immunotherapy on tumors." (PMID 37061706, 2023). "Activation of cGAS-STING signaling may differentially affect diverse cell types in the TME, but how cGAS-STING activation mediates immunosuppression, conveying a tumor-promoting effect, remains poorly defined." (PMID 37221584, 2023). "Activation of the cGAS–STING pathway in cancer influences the polarization of pro-tumorigenic macrophages M2 into anti-tumorigenic macrophages M1, attracts CD8+ lymphocytes, and reduces the expression of PD-L1 in tumor tissues." (PMID 37444620, 2023). "Of interest, increased cGAS-STING signaling is beneficial in certain pathologies, such as cancer, where AIM2 depletion promotes anti-tumor responses by enhancing STING-dependent type I IFN responses, suggesting specific AIM2 inhibitors are useful but require careful consideration." (PMID 37216118, 2023). "This favorable MMRd tumor response to ICB is probably due to high immune infiltration in the tumor microenvironment (TME), likely driven by multiple mechanisms, including a high neoantigen load and the activation of the cGAS-cGAMP-STING pathway." (PMID 37492581, 2023).
tumor (continued). "cGAS-STING participates in the remodeling of the tumor microenvironment (TME), which induces the production of antitumor cytokines such as interleukin 10 and invariant surface glycoprotein (ISG) that inhibit tumor growth." (PMID 36936940, 2023). "Tumours with a preponderance of cGAS+ micronuclei had low, but detectable, STING protein levels within cancer cells (cGAShighSTINGlow), whereas those with a paucity of cGAS+ micronuclei had higher STING protein expression (cGASlowSTINGhigh)." (PMID 37612508, 2023). "Furthermore, increasing evidence indicates that the cGAS‐cGAMP‐STING pathway responds to DNA damage and mediates inflammation and antitumor immunity by recruiting CTLs into the tumor microenvironment." (PMID 37986544, 2023). "The cGAS-STING pathway is essential for the antitumor immunity of CRC, the disruption of which may be a critical mechanism for immune escape of tumor cells." (PMID 37163421, 2023). "To further determine whether PRMT1-mediated change in PD-L1 expression is cGAS-dependent, we depleted endogenous cGAS in CT26, MC38, and 4T1 mouse tumor cells, and found a significant reduction in mPD-L1 expression in these cells." (PMID 37193698, 2023). "As the findings pointed to the expression of STING and cGAS for immune gene activation in cancer cells, we next turn to human lung tumour datasets to analyse expression levels of STING pathway genes in relation to immunological tumour features." (PMID 35794238, 2022). "But our results showed that, when autophagy was inhibited by CQ/HCQ, dsDNA fragments were presented more obvious aggregation in the cytoplasm of LLC cells and strengthened the protein expression levels of cGAS-STING pathway in the irradiated cells, and finally enhanced tumor IR-induced ATAE." (PMID 35847556, 2022). "In contrast to the proposed model, activation of cGAS-STING signaling could lead to cellular senescence and tumor suppression by promoting immunosurveillance." (PMID 35393420, 2022). "In addition, genomic instability upregulates the cGAS-STING pathway and activates anti-tumor immunity." (PMID 35846118, 2022). "However, many studies also suggested that cancer cells developed strategies to suppress the cGAS-STING pathway, likely for immune evasion during tumor development and progression." (PMID 35983076, 2022). "As many tumor types were shown to be “immune cold”, the inflammatory response elicited by CIN/aneuploidy through cGAS-STING pathway activation may actually play a tumor-promoting role." (PMID 36003402, 2022). "Activation of the interferon response in cancer cells, possibly by genomic instability through the cGAS–STING pathway, may affect immune cells in the tumor microenvironment and the tumor response to immunotherapies." (PMID 36428720, 2022). "Inhibition of cGAS and STING in tomor cells can prevent tumor metastasis." (PMID 35720348, 2022). "In addition to critical roles in innate immune responses to microbial pathogens, the cGAS-STING pathway is also involved in cellular senescence and anti-tumor immunity." (PMID 35973990, 2022). "By importing cGAMP from the TME, tumor cells that have a lower level of CIN or those with less cGAS expression can still activate the pro-tumor signaling downstream of STING, e.g. the noncanonical NF-κB pathway." (PMID 35325182, 2022). "The cGAS-STING pathway could induce the expression of type I interferon to activate antitumor immunity in DC cells and tumor cells." (PMID 35248033, 2022). "Given that type I IFN signalling induces CD8+ T‐cell responses against tumours, and that cGAS/STING signalling pathway promotes type I IFN production and adaptive immunity, the expression of cGAS/STING, IFN‐b and downstream chemokines were detected in NSCLC cells." (PMID 35415876, 2022).
tumor (continued). "At last, released Mn2+ ions and cytosolic damaged DNA collectively activated the cGAS/STING pathway, promoting the secretion of Type I IFN, enhancing the cytotoxic activity of CTL and NK cells, and demonstrating a strong anti-tumor immune response to inhibit tumor growth." (PMID 35748543, 2022). "In the present study, we observed that in tumor tissues without cGAS-STING signaling, cytotoxic CD8 + T cells are more distant from the tumor periphery, and their infiltration within the adjacent stromal tissue and toward the cancer cells is suppressed." (PMID 35773436, 2022). "The cGAS-STING-TBK1-IRF3 signaling pathway, a significant part of the innate immune system, is thought to be a broader immunotherapy strategy because it enhances tumor immunogenicity." (PMID 35806118, 2022). "Indeed, we compared the activation of cGAS-STING signaling in both SENP3-WT- and SENP3–9A tumor cells." (PMID 35869062, 2022). "From a mechanistic perspective, Mn2+ could directly bind with cGAS to enhance their dsDNA-sensitivity and cGAMP-producing enzymatic activity, thus stimulating the downstream STING signaling even under low levels of tumor-derived dsDNA29–31." (PMID 36167857, 2022). "In the distal tumor, the expressions of these proteins of cGAS-STING pathway had no changes after IR in PD-L1 wt mice but were still obviously increased in PD-L1−/− mice after IR." (PMID 35847556, 2022). "Therefore, the cGAS–STING signaling pathway is crucial to defend pathogen infection and tumor progression." (PMID 35536585, 2022). "In addition, it can detect cytosolic double-stranded DNA (dsDNA) released by tumor and dead cells via cyclic guanosine monophosphate–adenosine monophosphate (cyclic GMP–AMP or cGAMP) synthase (cGAS) activity." (PMID 36683857, 2022). "Combining xenograft immunofluorescence studies and state-of-the-art FRET FLIM techniques, we observed that osimertinib treatment, non-autonomously activated cGAS leading to cGAMP production in tumor cells, activating STING in TAMs." (PMID 35347108, 2022). "The combination treatment stimulated cGAS in cancer cells to produce cGAMP, which did not elicit type-I IFN production in tumor cells, but caused macrophages to produce type-I IFN." (PMID 35347108, 2022). "The cyclic GMP-AMP synthase (cGAS)-stimulator of interferon genes (STING) pathway is an innate immune pathway that results in the upregulation of immune cell recruiting-cytokines and anti-tumor efficacy." (PMID 35773436, 2022). "Our results also demonstrate a significant fraction of tumours that display STING expression in the absence of cGAS staining." (PMID 36612217, 2022). "Interestingly, tumor cells too, have devised ingenious ways to use the mitochondrial DNA mediated cGAS-STING-IRF3 response to promote neoplastic transformations and develop tumor micro-environments." (PMID 35223833, 2022). "In addition to antiviral immunity, cGAS-STING axis is also involved in cellular senescence and anti-tumor immunity." (PMID 35973990, 2022). "CIN in cancer cells has been reported to activate the cGAS–STING innate immunity pathway via micronuclei formation, thereby influencing tumor immunity and tumor progression, inducing sequential chromosomal segregation errors that promote cell invasion and metastasis in a STING-dependent manner." (PMID 36467504, 2022). "Emerging studies have reported a functional link between the cGAS-STING pathway and tumor diseases." (PMID 35983076, 2022). "The cGAS-STING pathway can activate type I IFN and have crucial roles in anti-tumor immunity." (PMID 35889509, 2022). "To investigate the therapeutic efficacy of the cooperative cGAS-STING nanoagonist in vivo, we constructed immunocompetent 4T1-luc tumor-bearing mice, which is a well-established animal tumor model with poor immunogenicity and low response rate to existing immunotherapeutic modalities." (PMID 36167857, 2022).
tumor (continued). "The cuprotosis related signatures could reshape tumor immunity in the ccRCC microenvironment via cGAS-STING signal, thus activating tumor antigen-presenting process." (PMID 36581992, 2022). "Activation of cGAS-STING signaling pathway has a bidirectional effect, which can not only activate immune-supporting cells to play an antitumor role but also create an immunosuppressive environment, thus promoting tumor formation and metastasis." (PMID 35983076, 2022). "In recent years, it was found that DNA from various sources could enter the cytosol and activate the cGAS-STING pathway: a DNA-driven immune response critical in host defense, inflammation, and tumor immunity." (PMID 35565197, 2022). "The strength and duration of cGAS-STING activation, possibly combined with other molecular and cell alterations, may define the outcome towards tumor promotion or suppression." (PMID 35393420, 2022). "In this regard, several cGAS-STING agonists, including STING-binding molecules and cGAMP derivates, have been developed, as apart from synergize with ICIs, they can enhance the antitumor effect of tumor vaccines, chemotherapy and radiotherapy." (PMID 35251003, 2022). "PARPi treatment leads to the accumulation of dsDNA in the cytoplasm, which activates the cGAS-STING-TBK1-IRF3 innate immune pathway, enhances type I IFN response, increases the number of tumor-infiltrating lymphocytes and induces the immunogenic microenvironment." (PMID 35906622, 2022). "We originally speculated that the cGAS agonist would also have a radiosensitizing effect, because type I IFN is known to show a radiosensitizing effect against various tumor cells including HNSCC cells." (PMID 35563740, 2022). "Also the cGAS-STING pathway, which is known to have important implications in anti-tumor immunity, can in some cancers promote inflammation-driven carcinogenesis, for example in brain metastasis or skin cancer." (PMID 34480199, 2022). "Another study discovered that the natural product rocaglamide specifically damages mtDNA and promotes its cytoplasmic release, which stimulates the activation of cGAS-STING signaling, resulting in increased natural killer (NK) cell infiltration and tumor growth suppression in NSCLC42." (PMID 35978045, 2022). "However, when they escape elimination by the host, established tumors induce a persistent inflammatory microenvironment, and chronic engagement of the cGAS-STING pathway and its corresponding SASP represent a driver of tumor progression." (PMID 36003402, 2022). "We speculated that the unique characteristics of cGAS-STING genes in KIRC and KIRP may be related to the unique tumor microenvironment." (PMID 35983076, 2022). "cGAS/STING is essential for control of both bacterial and viral pathogens, and cGAS/STING can also be triggered by host genomic DNA in the presence of tumor cells." (PMID 36059473, 2022). "Studies have revealed that tumor cells with high chromosomal instability (CIN) can activate the cGAS–STING (cyclic GMP-AMP synthase-stimulator of interferon genes) pathway through cytoplasmic DNA to produce inflammatory factors, thereby promoting tumor metastasis." (PMID 35163710, 2022). "This could have far-reaching implications for other pathologies, as regulation of the cGAS/STING pathway is fundamental in various inflammatory diseases and in tumor immunity and thus is a current focus of intensive drug discovery research efforts." (PMID 36255240, 2022). "DNA damage in tumor cells can result in chromosome mis-segregation during mitosis, leading to micronuclei generation that can also result in an accumulation of NAS in the cytoplasm and activation of the cGAS/STING pathway." (PMID 35602594, 2022). "Next, IHC was used to examine the expression of SOX2, cGAS, STING, ki67, CD3 and CD8 in tumours." (PMID 35415876, 2022).